MYC (MYC proto-oncogene, bHLH transcription factor)
Diseases named in the same sentence as MYC in open-access papers (continued):
Sharing a sentence is not in itself a finding about the gene and the disease.
lymphoma (continued). "This compound was effective against lymphoma cells with MYC rearrangement from two different patients that were co-cultured with cancer associated fibroblasts." (PMID 28055963, 2017). "The phenotype of lymphoma depends on the developmental step in which MYC overexpression occurred and on the specific genetic process that affected its dysregulation." (PMID 28375188, 2017). "The second group, “MYC-complex” included lymphomas with IG-MYC fusions or non–IG-MYC fusions that have a high chromosomal complexity score (≥6), an IGH-BCL2 fusion, BCL6 breakpoint, or any combination of these." (PMID 28379189, 2017). "Recent studies identified that 10% of lymphomas that morphologically and phenotypically resemble BL (including pediatric BLs) lack detectable MYC rearrangements, by either fluorescence in situ hybridization (FISH) or classical karyotyping." (PMID 28375188, 2017). "Over the past few years, MYC rearrangement and activity have been the focus of lymphoma research and clinical trials." (PMID 28375188, 2017). "The clinical significance of c-MYC rearrangement in B-cell lymphomas correlates with overall genetic context of the lymphoma." (PMID 28379189, 2017). "Combination epigenetic therapy with BETi has shown promising synergistic effects, such as the cytotoxic activity of BETi, RVX2135, with the HDAC inhibitors SAHA or LBH-589 in MYC-induced lymphoma in mice." (PMID 28505071, 2017). "In BL, there is a higher incidence of MYC translocations to Ig heavy chain loci, in comparison to other types of lymphomas where MYC is translocated to Ig light chain loci, or to other non-Ig loci." (PMID 28375188, 2017). "They conclude that in cHL and ALCL STAT-mediated BATF3 expression is essential for lymphoma cell survival and promotes MYC activity, indicating a new oncogenic axis in these lymphomas." (PMID 29057015, 2017). "The first group, “MYC-simple” is defined as lymphomas with immunoglobulin (IG)-MYC fusions and a low chromosomal complexity score (<6) that lacked IGH-BCL2 fusions and BCL6 breakpoints." (PMID 28379189, 2017). "Recent studies expanded the concept to include double-expressing lymphoma (DEL) that co-overexpresses MYC protein with either of those proteins." (PMID 28595585, 2017). "By contrast, in some models of lymphoma and papillomatosis, MYC depletion instead gives rise to cell cycle arrest, apoptosis, and complete regression." (PMID 28333115, 2017). "In particular, they focused on the lncRNA that had the highest positive correlation with MYC expression in MYC-positive lymphomas, which they titled MYC-induced long noncoding RNA (MINCR)." (PMID 28947998, 2017). "It is believed that in those lymphomas, MYC overexpression arrests normal B cell development and results in cell reprogramming." (PMID 28375188, 2017). "Both in vitro and in vivo, the lipid-lowering alkaloid berberine (BBR) exhibited an anti-lymphoma activity through inhibiting MYC-driven downstream PCYT1A expression and inducing mitophagy-dependent necroptosis." (PMID 29057015, 2017). "The lymphoma cells show strong expression of c-MYC in the majority of cells by immunohistochemistry." (PMID 28379189, 2017). "We have previously shown that an increase in MYC expression is observed in spleens and livers from two month old and also in the fully formed lymphomas from older mice when comparing Smurf2T/T to wild-type C57BL/6 mice." (PMID 28107482, 2017). "All of these functions account for MYC being an important biomarker for various lymphoma subtypes, uniformly as a secondary genetic alteration that usually contributes to an aggressive course of the disease." (PMID 28375188, 2017).
lymphoma (continued). "Recently, it was demonstrated that a double-hit lymphoma caused by multiple genetic aberrations, such as the MYC/8q24 locus and BCL2/18q21.3 locus can give rise to a unique subset of lymphomas." (PMID 28209136, 2017). "Consistent with this suggestion, it has been shown that inactivation of MYC led to tumor regression in vivo through the induction of senescence in hepatocellular carcinoma and lymphoma cells." (PMID 29050242, 2017). "The three lymphoma cell lines were treated with increasing concentrations of the c-MYC inhibitor, LY294002, Rapamycin, SB203580, PD98059 as well as with 2-DG or vehicle for 48 h and the percentage of viable cells compared to controls was assessed." (PMID 28724379, 2017). "Inhibition of c-MYC therefore is an attractive strategy to inhibit both the altered glucose metabolism and proliferation in lymphoma cells." (PMID 28724379, 2017). "Here we describe our search for effective drugs for primary refractory lymphoma cells with MYC rearrangement." (PMID 28055963, 2017). "In low-grade B-cell lymphomas, acquisition of c-MYC rearrangement usually results in transformation into highly aggressive lymphomas, with some exceptions." (PMID 28379189, 2017). "In lymphomas, c-MYC genetic abnormalities are restricted almost exclusively to B-cell lymphomas, and include primarily rearrangements and amplifications." (PMID 28379189, 2017). "PI3K as well as MYC act as major determinants of glucose and glutamine metabolism in lymphoma cells by regulating essential enzymes of these metabolic pathways." (PMID 29245936, 2017). "In Burkitt lymphoma cells, the down regulation of MYC results in inhibition of lymphoma cell growth." (PMID 28362357, 2017). "Administration of such nanoparticle-loaded T-cells to mice with aggressive MYC-driven lymphoma resulted in several magnitudes of improved drug uptake in tumor-bearing lymph nodes leading to tumor regression." (PMID 28665315, 2017). "For example, enforced BCL-2 oncogene expression inhibits MYC-induced apoptosis and cooperates with MYC to induce neoplastic transformation in murine lymphomas and medulloblastomas." (PMID 28333115, 2017). "An FDG uptake assay was established and uptake of FDG by lymphoma cells was determined after incubation with inhibitors of the c-MYC and the PI3K signalling pathways that are known to be activated in lymphoma cells and able to regulate glucose metabolism." (PMID 28724379, 2017). "MYC overexpression is typical for the aggressive type of lymphoma with the GCB phenotype, in which it cooperates with other factors influencing signaling cascades that contribute to the process of lymphomagenesis." (PMID 28375188, 2017). "In lymphoma, c-MYC activation occurs by several molecular mechanisms including translocations, amplification, mutations, altered intracellular localization of the c-MYC protein or miRNA-dependent mechanisms." (PMID 28724379, 2017). "Although the role of miR-17-19b (a truncated version of miR-17-92 cluster) is well documented in MYC-driven B cell lymphomagenesis, little is known about the function of the cluster in the maintenance of full-blown lymphomas." (PMID 26977435, 2016). "For instance, the well-known proto-oncogene and transcription factor c-MYC plays critical roles in MM pathogenesis and progression and is a strong driver of oncogenesis in lymphoma and MM models." (PMID 27494872, 2016). "“Double-expresser” lymphomas are defined based on IHC stains with MYC and BCL2 staining in more than a specified proportion of tumor cells." (PMID 27606052, 2016).
lymphoma (continued). "Besides retroviral insertion or transduction of human c-MYC leading to the development of lymphomas and carcinomas, amplification of MYC alleles has been observed in colon carcinoma, neuroblastoma, and lung cancer leading to the discovery of the N-MYC and L-MYC paralogs." (PMID 27313991, 2016). "In contrast, in another study, MYC/BCL6 (n = 13) showed significantly worse survival than MYC/BCL2 DHL (n = 20) after exclusion of triple-hit lymphoma." (PMID 26573234, 2016). "Nevertheless, the prognostic value of isolated MYC translocation (single-hit lymphoma, SHL) has remained controversial due to the limited studies with conflicting conclusions." (PMID 27825110, 2016). "Overexpression of oncoproteins such as MYC can also lead to inappropriate mRNA translation and eIF4E accelerates development of MYC-driven lymphoma." (PMID 27579538, 2016). "MYC levels further increase at the transition to frank lymphomas and there is clear evidence for further increases in MYC levels during progression of several tumor entities, as for example in APC-mutant colorectal tumors." (PMID 27460974, 2016). "In conclusion, our findings demonstrate that MCL-1 is critical for the survival of c-MYC overexpressing lymphoma-initiating cells and hence for development of lymphoma." (PMID 26962682, 2016). "In cancer cells, PRPS2 has been reported to be involved in nucleotide metabolism in melanoma and lymphoma and hence is proposed to be a potential therapeutic target for MYC-overexpressing cancers." (PMID 27448979, 2016). "In this study, the authors identify a panel of targets co-regulated by miR-17-19b and in MYC-driven lymphoma and unravel the molecular mechanism through which miR-17-19b inhibits MYC translation." (PMID 26555894, 2015). "Since PIM1 has been shown to promote c-MYC-dependent transcriptional activity, we sought to identify possible PIM1 and c-MYC target genes in lymphoma cell lines." (PMID 26643319, 2015). "Accordingly it has been recently demonstrated that tumours bearing high levels of oncogene-induced replicative stress, such as MYC driven aggressive lymphoma mouse models and neuroblastoma, are sensitive to single agent CHK inhibitors." (PMID 25544753, 2015). "Overexpression of the miR-17-92 cluster members was a consequence of such an amplification, as found in leukemia/lymphoma cell lines bearing 13q amplification, or due to an overexpression of MYC." (PMID 26305986, 2015). "In both λ-MYC lymphomas, a modest increase of miR-17-19b led to impaired proliferation, a reduction in G1-to-S transition and a significant increase in the fraction of apoptotic cells." (PMID 26555894, 2015). "They focused on an lncRNA that they named MYC-induced long non-coding RNA (MINCR) and that showed a strong correlation with MYC expression in MYC-positive lymphomas." (PMID 26640600, 2015). "The acute perturbation of miR-17-19b levels in aggressive lymphomas allowed us to appreciate the fine equilibrium between miR-17-92 and MYC in tumour cells and the biological consequences of this tight balance on in vivo tumour growth." (PMID 26555894, 2015). "The term ‘double‐hit’ lymphoma was originally used to describe aggressive DLBCL with MYC and BCL2 translocation, then subsequently extended to include those with MYC and BCL6 translocation." (PMID 27347428, 2015). "Surprisingly, our analysis showed that MYC itself is downregulated upon acute induction of miR-17-19b in lymphoma cells." (PMID 26555894, 2015). "We have recently shown that FOXO1 activation almost completely abolished MYC protein expression in lymphoma cells." (PMID 26568463, 2015). "Patients with both MYC and BCL2 copy number aberration had similar outcomes to those with classic double-hit lymphoma (DHL) or protein double expression lymphoma (MYC and BCL2/BCL6 coexpression)." (PMID 26416427, 2015).
lymphoma (continued). "Similar to our previous findings on the MYC-dependent mouse lymphoma cell line iMycEμ, Ab to p50 shifted two NF-κB-specific bands to higher molecular-weight positions on EMSA gels, whereas Ab to p65 or c-Rel shifted only the upper or lower band, respectively." (PMID 25838973, 2015). "In this study, we address the function of miR-17-19b in established MYC lymphomas, at a stage when MYC has pervasively reprogrammed the transcriptome of the tumour cell." (PMID 26555894, 2015). "Deregulation of c-MYC is therefore a common feature amongst aggressive lymphoma either occurring as an isolated event or with additional rearrangements." (PMID 26643319, 2015). "To investigate the role of miR-17-19b in full-blown B cell lymphomas, we perturbed the system by increasing the expression of the cluster in λ-MYC lymphoma B cells, whose endogenous miR-17-19b levels are comparable to those of human BL." (PMID 26555894, 2015). "Here we investigate the role of miR-17-19b in c-MYC-driven lymphomas by integrating SILAC-based quantitative proteomics, transcriptomics and 3′ untranslated region (UTR) analysis upon miR-17-19b overexpression." (PMID 26555894, 2015). "Like BL cells, λ-MYC lymphoma cells, especially when apoptotic, were able to activate MMP2 and MMP12 expression in macrophages in vitro and promote the expression of a variety of SS-TAM markers in bone marrow-derived macrophages (BMDMs)." (PMID 25702581, 2015). "To assess the biological relevance of miR-17-19b modulation in lymphoma maintenance, we chose two independent λ-MYC lymphomas showing endogenous levels of miR-17-19b similar (#2567) or lower (#2646) than those of human BL." (PMID 26555894, 2015). "The increased sensitivity to hypomorphic ATR reduction was observed in sarcomas expressing active forms of H-RasG12V, acute myeloid leukemia driven by MLL-ENL, and in c-MYC-driven lymphoma." (PMID 26295265, 2015). "CKS1B is transcriptionally induced by c-MYC and negatively regulates the cyclin-dependent kinase (Cdk) inhibitor p27Kip1 in lymphoma, supporting c-MYC tumorigenesis." (PMID 25477524, 2015). "The enforced expression of the truncated version of the cluster, miR-17-19b, was shown to synergize with MYC in accelerating tumorigenesis in the Eμ-MYC mouse lymphoma model." (PMID 26555894, 2015). "The region in MYC, which is responsible for MYCBP2 interaction, is frequently mutated in Burkitt's and AIDS-associated lymphomas, indicating MYCBP2 suppress MYC activity." (PMID 26517351, 2015). "In conclusion, our data demonstrate that miR-17-19b sustains homeostasis of MYC-driven lymphomas by fine-tuning MYC expression, thus protecting tumour cells from harmful effects linked to excessive MYC levels." (PMID 26555894, 2015). "These aggressive lymphomas also have additional oncogenic alterations that cooperate with MYC dysregulation by counteracting especially its proapoptotic function." (PMID 26416427, 2015). "At the molecular level, we unravelled the inhibitory effect of miR-17-19b on MYC expression and function in established MYC-driven lymphomas." (PMID 26555894, 2015). "We first investigated a model of aggressive B cell lymphoma in immunocompetent mice, λ-MYC lymphoma, which also displays starry-sky features with frequent TAMs and apoptotic events." (PMID 25702581, 2015). "The aggressive nature of double-hit and triple-hit lymphomas is likely due to the concurrent rearrangement of both the pro-proliferative c-MYC oncogene and the anti-apoptotic BCL2 oncogene." (PMID 26654227, 2015). "Recent reports have identified MYC-positive lymphoma as a subtype with poor disease prognosis, even resistant to high-dose chemotherapy and newly developed bio-therapeutic agent." (PMID 24586676, 2014). "In genetically engineered mouse models, reduction of ATR prevented MYC-driven lymphomas or pancreatic tumors." (PMID 25495526, 2014).
lymphoma (continued). "For example early studies using an inducible c-MYC model showed that activation of c-MYC promoted lymphoma formation that regressed upon removal of c-MYC expression." (PMID 24796395, 2014). "In the clinical setting, lymphoma patients exhibit a striking correlation between high levels of MYC and CHK1." (PMID 24586676, 2014). "For example, translocations commonly found in Burkitt’s lymphoma place the MYC oncogene in control of intronic and 3’ IGH enhancers, ultimately leading to deregulated expression of MYC and the development of lymphoma." (PMID 25473436, 2014). "Concurrent BCL2 and MYC rearrangements were found in four cases comprising two extranodal (gastric and brain) and two nodal lymphomas." (PMID 24887414, 2014). "We selected a panel of human lymphoma cell lines and divided them into c-MYC high and low groups (BioGPS database)." (PMID 25495526, 2014). "MYC rearrangements, either alone or in combination with BCL2 rearrangements (“double-hit” lymphomas), have been associated with resistance or a poor response to therapy and inferior survival in systemic DLBCL." (PMID 25479599, 2014). "After a 4 h drug treatment, we noted a significant and dose-dependent decrease in c-MYC protein levels in multiple lymphoma cell lines, correlating with a concurrent decrease in c-MYC mRNA expression (respectively)." (PMID 25495526, 2014). "In this unrelated series, lymphomas with BCL2 or MYC translocations showed a minimum of 32% and 25% cells with signals indicative for rearrangements, respectively." (PMID 24733537, 2014). "It appears that the result of Ccr7/9 activation in Runx2/MYC lymphomas is likely to be paracrine growth stimulation, as expression of the cognate ligands (Ccl19, 21, 25) is restricted to thymic stromal cells." (PMID 24586197, 2014). "The functionality of this concept was demonstrated by decoding the metabolic basis of synthetic lethality induced by metabolic inhibition of senescent lymphoma cells and in MYC-driven cancer cells after ARK5 inhibition." (PMID 25035808, 2014). "In order to further validate PRKDC dependency in other MYC-driven cancers, we chose to examine c-MYC in human lymphoma cell lines using the potent PRKDC inhibitors, NU-7441 and KU0060648." (PMID 25495526, 2014). "The RNA-binding protein Tristetraprolin (TTP, ZFP36) functions as a tumor suppressor that impairs the development and disables the maintenance of MYC-driven lymphoma." (PMID 25541715, 2014). "Double-hit (DH) and triple-hit (TH) lymphomas are transformed B-cell lymphomas that are generally defined by the presence of MYC gene rearrangement together with either BCL2 and/or BCL6 gene rearrangement." (PMID 24887414, 2014). "We examined c-MYC protein expression levels in lymphoma cell lines treated with the PRKDC inhibitor, KU0060648." (PMID 25495526, 2014). "MYC and Runx2 transgenes each cooperate with MoMLV to accelerate lymphoma onset to around 60 days post-infection." (PMID 24586197, 2014). "This condition suggests that BL with CK are indeed different from other aggressive MYC-rearranged lymphomas, usually showing wider genetic complexity." (PMID 24079473, 2013). "In normal tissue c-MYC expression is tightly regulated, whereas in lymphomas and other tumors c-MYC is invariably deprived of its physiological control and constitutively switched on." (PMID 24130880, 2013). "BET bromodomain inhibition appears to break Rituximab resistance in lymphoma B cells showing coincident MYC and CYCLON overexpression." (PMID 23828858, 2013). "This indicates that CYCLON overexpression is an autonomous tumour growth driver that cooperates with MYC to drive lymphoma progression." (PMID 23828858, 2013). "Taken together, these data raised the possibility that CYCLON is a key downstream effector of oncogenic MYC signalling in lymphoma." (PMID 23828858, 2013).